HIF1A (hypoxia inducible factor 1 subunit alpha)
Diseases named in the same sentence as HIF1A in open-access papers (continued):
Sharing a sentence is not in itself a finding about the gene and the disease.
cancer (continued). "HIF1α could thus play a central role in cancer progression that FDG uptake represents." (PMID 23718763, 2013). "Therefore, HIF-1α is a fundamental factor regulating cancer-specific glucose metabolism." (PMID 24216696, 2013). "Interestingly the expression of HIF1α can also be increased under a normoxic environment at all three levels of regulation (transcription, translation and protein stability) and overexpression of HIF1α under normoxia has been detected in various cancers." (PMID 23342109, 2013). "These contradictory effects may limit the anti-cancer effect of HIF-1α inhibitors." (PMID 23028659, 2012). "Therefore, HIF-1α-targetting therapies provide new insights into the treatment of cancer." (PMID 23300882, 2012). "Therefore, soy isoflavone-mediated inhibition of HIF-1α activation by oxidative stress could render cancer cells more radiosensitive." (PMID 22997517, 2012). "Thus, it was hypothesized that inhibition of HIF-1α signal pathway would therefore offer an innovative strategy for anti-angiogenesis and anti-metastasis in cancer therapy." (PMID 23300882, 2012). "However, if HIF-1α inhibitors have the additional effect of inducing cell cycle arrest or cell death, they might be better propositions as anti-cancer agents." (PMID 23028659, 2012). "Thus, HIF-1α is viewed as an excellent target for the development of novel cancer therapeutics." (PMID 21819554, 2011). "Additionally, recent work at the NCI suggests that prolonged Topo 1 inhibition can mediate a novel Topo 1-dependent hypoxia-inducible factor 1 alpha (HIF-1α) inhibition mechanism, another promising cancer drug target that has been the subject of intense research and screening efforts." (PMID 22081768, 2011). "The ERβ/HIF-1α/ARNT pathway may play an important role in cancer progression." (PMID 21435239, 2011). "Furthermore, Treg recruitment by CXCL12/CXCR4 in these cancers may potentially be modulated by treatment directed against the HIF-1α pathway." (PMID 21521526, 2011). "Since both HIF-1α and c-Myc play important roles in cancer cell energy metabolism, together these results suggest that targeted cancer cell metabolism through modulation of HIF-1α and c-Myc expression may improve the efficacy of ADI-PEG20 in treating Arg auxotrophic tumors." (PMID 21152246, 2010). "Finally, it remains important to elucidate the underlying mechanisms by which Arg deprivation regulates c-Myc and HIF-1α that may have global effect on cancer metabolism in the Arg auxotrophic cancer cells." (PMID 21152246, 2010). "However, little is known about the role of HIF-1α in hereditary breast carcinogenesis with only one report in a small series (n=30) suggesting overexpression of HIF-1α present in a higher frequency in BRCA1-related cancers than sporadic cancers." (PMID 19724277, 2009). "Despite having 48% amino acid sequence identity, HIF-1α and HIF-2α have diverse functions and gene targets, and their roles change in various cancers and cell types." (PMID 41614928, 2026). "Collectively, HIF‐1α‐mediated FA uptake leads to FA accumulation, which in turn amplifies HIF‐1α activity, exacerbating cancer." (PMID 41160815, 2026). "HIF1A and VEGFA gene expression (p = 0.0199 and p = 0.0239, respectively) differed significantly between the control and cancer groups in pre-menopausal women." (PMID 39888575, 2026). "In cancer-affected tissue, significant correlations of VEGFA with HIF1A and EPAS1 were weak and only in post-menopausal cases." (PMID 39888575, 2026). "Cancer cell viability was measured by Resazurin cytotoxicity assay and the gene and protein expression of APC, KRAS, TTN, HIF-1α, HIF-1β, and GLUT-1 were measured using rtPCR and ELISA." (PMID 41797969, 2026). "The target genes of HIF-1α and HIF-2α are thought to be negatively regulated by HIF-3α, and the HIF-1α subunit, in particular, is essential for the development of cancer." (PMID 41614928, 2026).
cancer (continued). "HIF1A enhances cancer cell invasiveness by activating the Sonic Hedgehog pathway and upregulating DEC2, which further amplifies HIF1A activity, driving metabolic reprogramming, angiogenesis, and invasion." (PMID 41048631, 2025). "Serving as a key glycolysis‐related enzyme downstream of HIF‐1α during hypoxic conditions, the role of PDK1 in regulating EMT has been documented in various cancers." (PMID 40176272, 2025). "The suppressive effect of HIF1α on IFN-1 (IFNα and IFNβ) or IFN-2 (IFNγ) was described by others in a hypoxic microenvironment in cancer as well as in SARS-CoV-2 infection." (PMID 40570045, 2025). "Both HIF-1α and NOTCH1 pathways are known to regulate hypoxia responses, angiogenesis, and cancer stem cell renewal, making them key drivers of aggressive cancer phenotypes 42-44." (PMID 40302812, 2025). "HIF-1α and HIF-1β are primary oxygen-limiting sensors and their induction support cancer cell proliferation during hypoxia and diverse metabolic alterations." (PMID 40963621, 2025). "This binding pattern of HIF1α and MYB was confirmed by ChIP-qPCR assay on select sites in additional cancer cell lines." (PMID 40680814, 2025). "The upregulation of glycolysis through HIF1α target genes (such as HK2, GLUT1, PDK1, and LDHA) provides cancer cells with rapid ATP production and biosynthetic intermediates." (PMID 39807625, 2025). "The role of HIF-1α in the IVM presents both challenges and opportunities for advancing cancer immunotherapy." (PMID 39981236, 2025). "In multiple cancers, including HNSCC, HIF-1α translocates to the nucleus to promote malignant cell survival." (PMID 40392349, 2025). "The regulation of HIF1α, LDHA, and PDK1 by the ZFAS1-STAT3 axis is a novel insight that can have significant implications for understanding and targeting cancer metabolism." (PMID 40697388, 2025). "HIF-1α enhances the expression of ATP-binding cassette (ABC) transporters, which directly efflux chemotherapeutics out of cancer cells." (PMID 41007213, 2025). "In summary, HIF-1α and MYC are key drivers of metabolic reprogramming, enabling cancer cells to adapt to hypoxia and sustain growth through glycolysis, lipid synthesis, and biosynthesis." (PMID 41281744, 2025). "Critical targets such as TNF, EGFR, ESR1, HIF1A, HSP90AA1, and SRC were involved in pathways including chemical carcinogenesis, PI3K‐Akt signaling, proteoglycans in cancer, receptor activation in chemical carcinogenesis, and immunomodulation." (PMID 40144560, 2025). "These mutations overcome the cell cycle arrest mediated by hyperactive Hif-1α and/or autocrine TGF-β signaling, helping cancer cells combine sustained proliferation with an invasive mesenchymal state." (PMID 40238833, 2025). "In hypoxia, HIF1-α also induces the expression of NR2F1-AS1, which positively regulates its neighboring gene NR2F1, to promote cancer cell proliferation, migration and invasion by activating AKT/mTOR signaling." (PMID 39940704, 2025). "Under such conditions, various processes such as cancer cell proliferation, migration, invasion, and EMT are highly induced through the activation of HIF-1α." (PMID 39911856, 2025). "Downregulation of succinate dehydrogenase (SDH) and fumarate hydratase (FH) activities, which are common hallmarks of cancers, results in the accumulation of succinate, inhibition of PHD activity and induction of HIF-1α." (PMID 40264757, 2025). "By highlighting the interactions between stress responses and key cellular signaling pathways, such as HIF-1α and NOTCH1, this research underscores the significance of stress responses in cancer biology." (PMID 40302812, 2025).
cancer (continued). "Two structurally characterized receptors—the human androgen receptor (HAR, PDB ID: 1E3G) and hypoxia-inducible factor 1-alpha (HIF-1α, PDB ID: 3KCX), known for their involvement in cancer-related pathways, were used for molecular docking investigations." (PMID 40362546, 2025). "For instance, cancer cell-derived EVs containing TGF-β, Src, Wnt3, and HIF1α are taken up by TAMs, which subsequently release membrane blebs, transferring these components to stromal cells." (PMID 40574844, 2025). "Furthermore, our data demonstrate that the continued inhibition of HIF-1α can result in prolonged viral replication, highlighting the potential unwanted side effects associated with the use of HIF-modulating therapeutics in the context of other diseases, such as cancer." (PMID 40244000, 2025). "HIF-1α, a key transcriptional regulator of oxygen homeostasis, exerts an activating influence on the transcription of glucose transporters and glycolytic enzymes, and the subsequent hypoxia-induced glycolysis increase could be utilized by cancer cells for survival and development." (PMID 40775462, 2025). "Specifically, the study focused on the modulatory effects of this combination on the HIF-1α signaling pathways, which mediate angiogenesis, apoptosis, evasion, proliferation, and the transition from epithelial to mesenchymal stage (EMT) in cancer cell lines." (PMID 40205002, 2025). "Above all, these results have been shown that circ_0000977/miR-153/ HIF-1α /ADAM10 axis can possibly be used as immune-sensitizers in the treatment and/or prevention of cancer progression." (PMID 39928285, 2025). "Cu triggers angiogenesis, mainly stabilizing the hypoxia-inducible factor 1 subunit alpha (HIF-1α), which further promotes the activity of proangiogenic factors and cancer." (PMID 41198664, 2025). "Leveraging drug screens, we discovered that ETS1-high cancers are vulnerable to HSP90 inhibitors (e.g., Alvespimycin), which suppress ETS1 by disrupting HIF1A-mediated transcriptional activation." (PMID 40777467, 2025). "In low oxygen environments, the lncRNA HOTAIR is expressed and serves as a ceRNA that binds to miR-217 thereby de-repressing HIF-1α and elevating levels of HIF in cancer cells." (PMID 39761690, 2025). "The expression of both PDKs and LDH-A is induced by HIF-1α; thus, PDH is considered a drug target not only for cancer treatment but also for other pathologies." (PMID 41155146, 2025). "Kruskal–Wallis test was employed to compare the protein expression differences of UBE2S, HIF‐1α, and FOXM1 in the adjacent tissues, HIN, LIN, and cancer tissues." (PMID 41427004, 2025). "Findings regarding hsa-miR-21-5p and its interaction with hypoxia-inducible factors HIF1A and HIF2A or its influence on VEGFA signaling highlight its impact on cancer progression and therapeutic implications." (PMID 40362695, 2025). "However, HIF-1α can also remain stable in normoxia in malignant cancer cells or after some treatment, namely pseudohypoxia, which is defined as a phenomenon in which many cancer cells have developed the ability to activate and utilize hypoxia-dependent pathways even in the presence of oxygen." (PMID 39757165, 2025). "Activation of SUCNR1 on TAMs, for instance, activates PI3K signaling and HIF-1α activation, triggering M2 TAM polarization and leading to immune suppression and cancer and TAM cell migration." (PMID 39796781, 2025). "Simultaneous upregulation of HIF1α and ME1 is observed at the cancer front, with ME1 expression being induced by hypoxia." (PMID 39996805, 2025). "This review explores cysteine alkylation as a cancer treatment strategy, focusing on Michael acceptors like curcumin and helenalin, which interact with transcription factors NF-κB, STAT3 and HIF-1α." (PMID 40507356, 2025).
cancer (continued). "Other drugs like EZN‐2968 and EZN‐2208 are being tested to inhibit the expression of HIF‐1α mRNA, leading to downregulating HIF‐1α protein in cancer cells." (PMID 40567251, 2025). "The outcomes of the IHC staining exhibited that the pattern of UBE2S expression was evident, namely, in the cytoplasm and nucleus, HIF‐1α and FOXM1 expression were major situated in the cancer cells nucleus." (PMID 41427004, 2025). "Since both HIF‐1α and A3AR are overexpressed in cancer, the link between A3AR stimulation and the modulation of HIF‐1α expression under hypoxic conditions has been explored." (PMID 40181576, 2025). "Studies have shown that HIF1A can interact with its downstream target proteins PKM2 and PHD3 (EGLN3), ultimately playing an important role in the reprogramming of cancer cell glucose metabolism." (PMID 40721814, 2025). "In contrast, HIF-1α binds with SP1 via the PAS-B domain, displacing c-MYC from binding multiple gene targets and hindering its role in cancer progression." (PMID 39470609, 2025). "It was shown that increased hsa-miR-21-5p maturation subsequently led to degradation of HIF1AN (HIF1A asparagine hydroxylase), an inhibitor of HIF1A, thus activating HIF1A-VEGFA signaling and promoting cancer progression." (PMID 40362695, 2025). "Using computational docking tools, the study compares how well these natural products and standard cancer drugs bind to key proteins such as NF-κB, STAT3 and HIF-1α." (PMID 40507356, 2025). "The complex interaction between hypoxia, HIF-1α, and the IVM represents a critical axis influencing cancer progression and therapeutic resistance." (PMID 39981236, 2025). "The upregulation of MUC1 expression is one of the downstream effects of HIF-1α activation, which is consistent with MUC-1-induced cancer cell migration and invasion." (PMID 40699805, 2025). "Epigenetic changes dysregulate HIF-1α and metabolic enzymes like fructose-bisphosphatase FBP1, PKM, and Lactate dehydrogenase A (LDHA) in CAFs, fueling cancer growth." (PMID 40230452, 2025). "Previous studies on cancer metabolism and inflammation have reported that the PKM2 dimer translocates to the nucleus and promotes HIF-1α-mediated transactivation." (PMID 40713487, 2025). "Recently, a published study has demonstrated that HIF-1α-induced MT2A accumulation can sequester mitochondrial copper to blunt apoptotic signaling, thereby promoting cancer cell resistance to cell death." (PMID 41211480, 2025). "The HIF family consists of oxygen-sensitive transcription factors, with HIF-1α and HIF-2α being the most studied in cancer." (PMID 40901111, 2025). "Here, we reported an underappreciated partner of ASH1L, transcriptional factor HIF-1α, which directly interacts and co-opts with ASH1L in regulating pro-metastatic genes in invading cancer cells." (PMID 40394007, 2025). "However, in some aggressive cancers, HIF-1α may remain stabilized in the presence of oxygen." (PMID 40358197, 2025). "Upon activation, they promoted cancer cell proliferation and prevented apoptosis via PI3K/Akt/mTOR signaling with increased protein levels of MYC and HIF1α and stimulation of the Warburg effect." (PMID 39714760, 2025). "For instance, Silibinin, a polyphenolic compound from milk thistle, impedes glycolytic metabolism by inhibiting HIF-1α/LDH-A, reducing PD-L1 expression on cancer cells, and enhancing immune response via the glycolytic pathway." (PMID 39897050, 2025).
cancer (continued). "This pseudohypoxic state, which sustains HIF1α signaling, is essential for promoting EMT and metastasis of cancer cells." (PMID 40701956, 2025). "HIFs, particularly HIF-1α and HIF-2α, regulate several genes related to cancer hallmarks such as invasion, metabolic reprogramming, angiogenesis, and therapy resistance, thus mediating a significant portion of the hypoxic response." (PMID 41732210, 2025). "Collectively, the present results support a coherent mechanistic framework linking hypoxia, HIF-1α stabilization, and TRPV1-mediated Ca2+ dynamics, with direct implications for therapeutic targeting in estrogen-responsive cancers." (PMID 41303593, 2025). "The liposomal complex inhibited invasion and metastasis by lowering the levels of VE-Cadherin, PI3K, VEGF, HIF-1α, FAK, and MMP-2, thereby inducing apoptosis in cancer cells." (PMID 40427522, 2025). "CAF-derived collagen/hyaluronan-induced ECM stiffness physically blocks T-cell infiltration and promotes prosurvival signaling pathways (e.g., HIF-1α and YAP) in cancer cells." (PMID 41348261, 2025). "We examined the roles of HIF-1α, MMP-9, and β-catenin as cancer-promoting factors, and we observed that the levobupivacaine treatment affected the expressions of HIF-1α and MMP-9 in an ACE2-dependent manner, whereas β-catenin was regulated independently." (PMID 41303321, 2025). "Additional pathways such as cell cycle regulation, xenobiotic metabolism by cytochrome P450 (CYP2C9), and nitrogen metabolism can influence cancer progression, although their direct links to the WWOX/HIF1A ratio require further investigation." (PMID 41007296, 2025). "The ROS-mediated stabilization of HIF-1α was also shown to activate the PI3K/Akt pathway, promoting cancer cell adaptation and survival in oxygen-deprived conditions." (PMID 39857427, 2025). "In non-small lung cancer (NSCLC) cell lines (A549 and H1650), hypoxia induces the expression of lncRNAs H19, HIF1-α, HO-1, MRP-1 and P-gp, resulting in increased migration and invasion of cancer cells along with an increase in cisplatin resistance." (PMID 39940704, 2025). "Targeting NF-κB-related pathways, including those mediated by HIF-1α and HIF-2α, seems to be a promising approach for reducing cancer stemness and improving therapeutic outcomes." (PMID 40420174, 2025). "Several of the markers selected to study TAM heterogeneity, including HIF1A, GMNMB, Activin A, and PD-L1, were also found to be expressed by cancer cells." (PMID 40406129, 2025). "FOXO activation occurs in response to hypoxia, predominantly through a HIF-dependent pathway involving HIF-1α and, to a lesser extent, HIF-2α, in normal mouse and human fibroblasts, as well as various cancer cells." (PMID 39965249, 2025). "Lysosomes also influence mitochondrial activity through signaling molecules such as reactive oxygen species (ROS), which can stabilize hypoxia-inducible factor 1-alpha (HIF-1α) and support cancer cell survival under low oxygen conditions." (PMID 41311372, 2025). "Targeting HIF-1α in the IVM offers a multifaceted approach to overcoming hypoxia-driven immunosuppression and therapeutic resistance in cancer." (PMID 39981236, 2025). "Hence, we speculated that HIF-1α might promote cancer progression by regulating glycolysis." (PMID 40775462, 2025). "Experiments conducted on cancer cell lines (HeLa, HCT116, and Hep3B) indicated that HIF-1α inhibits transcription and translation of DUSP2, leading to sustained ERK1/2 phosphorylation and increased chemoresistance." (PMID 40943262, 2025). "To date, several anti-hypoxia drugs based on HIF-1α, such as topotecan, and HIF-2α inhibitors, such as PT2399, have been clinically used for the treatment of cancer patients." (PMID 40004471, 2025).